PCAT7 (prostate cancer associated transcript 7)
Synonyms: PCAN-R2
Gene: Long non-coding RNA gene on chromosome 9 (94,554,599 to 94,603,990, forward strand). Ensembl gene ENSG00000231806.
Diseases named in the same sentence as PCAT7 in open-access papers:
PCAT7 is named in the same sentence as 11 diseases in open-access papers, as found by Europe PMC text mining. Sharing a sentence is not in itself a finding about the gene and the disease. The quoted sentences say what the papers report.
prostate carcinoma (6 papers, 2020 to 2024). A carcinoma that arises from epithelial cells of the prostate gland. "PCAT7 is crucial in prostate cancer bone metastasis, which is upregulated by the activation of TGF-β/SMAD signaling and β signaling, forming a positive feedback pathway." (PMID 36922569, 2023). "PCAT7 has been shown to induce malignant progression, metastasis, and poor prognosis of breast cancer, prostate cancer, nonsmall cell lung cancer, and nasopharyngeal carcinoma." (PMID 35371346, 2022). "In prostate cancer, upregulation of PCAT7 enhances bone metastasis and aggressive behavior of prostate cancer cells via EMT induction." (PMID 35773731, 2022). "lncRNA PCAT7 is upregulated in primary prostate cancer tissues with bone metastasis." (PMID 31925912, 2020). "Furthermore, TGF-β signaling can form a positive feedback loop with PCAT7 to enhance its expression, resulting in EMT induction and bone metastasis of prostate cancer cells." (PMID 35773731, 2022).
breast carcinoma (3 papers, 2022 to 2025). "Data from TCGA database showed that PCAT7 expression levels, as determined by ROC curve and OS curve analysis, were significantly associated with reduced overall survival in breast cancer patients." (PMID 40809023, 2025). "IHC staining confirmed that the expression of PCAT7 protein was increased in four different subtypes of breast cancer tissues compared with adjacent normal breast tissues." (PMID 40809023, 2025). "PCAT7 staining was higher in BRCA luminal A, luminal B, HER2, and TNB breast cancer tissues than in controls; PCAT7 was mainly located in the cytoplasm of the specimens, and staining was predominant in the tumor tissues." (PMID 40809023, 2025). "Ghaemi Z found that miR-326 can inhibit the occurrence of breast cancer by regulating the ERBB/PI3K pathway, and in addition, lncRNA PCAT7 can activate the ERBB/PI3K/AKT pathway to promote breast cancer progression." (PMID 35290409, 2022). "Abnormal expression of PCAT7 in BRCA tissues and cells promotes cancer cell proliferation, migration, and invasion while inhibiting apoptosis, and promotes malignant progression of breast cancer by regulating the expression of a range of downstream genes." (PMID 40809023, 2025).
bladder cancer (2 papers, 2021 to 2022). "Five commonly used CRLs were selected for experimental verification by qRT-PCR, including PCAT7, LINC01184 (SLC12A2-DT), MPP7-DT, FAM87B and UBE2Q1-AS1 in human bladder cancer tissues and normal bladder tissues (Normal bladder tissues are assigned to the low-risk group)." (PMID 36454396, 2022). "The results showed that PCAT7 and UBE2Q1-AS1 LncRNA genes were lowly expressed in human bladder cancer tissues, while LINC01184 (SLC12A2-DT), MPP7-DT, FAM87B were expressed to a great extent in human bladder cancer tissues." (PMID 36454396, 2022).
bone tumor (1 paper, 2020). "Consistently, the results indicated that PCAT7 was elevated in PCa tissues relative to that in ANT, and gradually increased from PCa/nBM and PCa/BM to metastatic bone tumor tissues." (PMID 31925912, 2020).
triple-negative breast carcinoma (1 paper, 2025). An invasive breast carcinoma which is negative for expression of estrogen receptor (ER), progesterone receptor (PR), and human epidermal growth factor receptor 2 (HER2). "In addition, luminal A, luminal B, HER2, and basal like triple-negative breast cancer samples were collected clinically to verify the expression of PCAT7." (PMID 40809023, 2025).
tumor (5 papers, 2020 to 2025). "Subsequent analyses revealed that the upregulation of PCAT7 was positively associated with advanced pathological characteristics, including Gleason score, tumor volume, lymph node metastasis, and bone metastasis status, and showed poor overall and disease‐free survival of PCa patients." (PMID 31925912, 2020). "Further studies on the role of PCAT7 in immune cell infiltration and tumor immune escape in the tumor microenvironment are needed to provide a new perspective and potential therapeutic targets in the field of immunotherapy." (PMID 40809023, 2025). "Bone metastasizing capacity of PCAT7-overexpressing prostate cancer cells was found to be notably enhanced in tumor bearing mice." (PMID 33511320, 2021). "In this study, we identified a PCa‐associated lncRNA, prostate cancer‐associated transcript 7 (PCAT7), also known as PCAN‐R2, which locates in chromosome (chr) 9q22.32 and has been reported to be involved in tumor progression." (PMID 31925912, 2020). "PCAT7 overexpression accelerated the onset of bone metastasis in tumor bearing mice." (PMID 33511320, 2021). "Moreover, upregulation of PCAT7 increased bone metastatic loci (X‐ray) and tumor burden (H&E), and shortened bone metastasis and overall survival of the mice, while silencing PCAT7 showed an opposite effect." (PMID 31925912, 2020). "Thus, it is hypothesized that elevated levels of PCAT7 result in the infiltration of immune cells, consequently promoting the development of the tumor microenvironment." (PMID 40809023, 2025). "To further screen out the desired lncRNAs, we utilized RT-qPCR assay to identify the top 5 lncRNAs (PCAT7, FAM83C-AS1, LINC00144, HMGB3P1 and AC016735.1) that were remarkably upregulated in CRC tissues as compared to corresponding non-tumor tissues." (PMID 33109776, 2020).
cancer (2 papers, 2021 to 2025). A tumor composed of atypical neoplastic, often pleomorphic cells that invade other tissues. "The most relevant module genes associated with PCAT7 are significantly enriched in immune and cancer-related pathways." (PMID 40809023, 2025). "Studies have demonstrated that PCAT7 is highly expressed in numerous malignant tumors, including lung cancer, BRCA, and prostate cancer, and has been associated with unfavorable prognoses." (PMID 40809023, 2025). "Paired dot plot showed that the expression level of PCAT7 protein in cancer tissues was higher than that in adjacent tissues (p < 0.001)." (PMID 40809023, 2025). "PCAT7 expression was higher in luminal A, luminal B, HER2, and basal-like triple negative breast (TNB) cancers compared with controls." (PMID 40809023, 2025).
PCAT7 also shares sentences with these, for which no sentence is quoted: nonsmall cell lung cancer (3 papers); nasopharyngeal carcinoma (2); bone metastasis (1); lung carcinoma (1).